PPAN-P2RY11 (PPAN-P2RY11 readthrough)
Gene: Protein-coding gene on chromosome 19 (10,106,223 to 10,114,780, forward strand). Ensembl gene ENSG00000243207.
Genetic constraint (gnomAD): Loss-of-function variants: 47 observed, 53.21 expected, observed/expected ratio (o/e) 0.88, 90% interval 0.7 to 1.13. The synonymous counts are far from expectation, so gnomAD's model fits this gene poorly and the ratio says little. Missense variants: 1,313 observed, 1,079.1 expected, observed/expected ratio (o/e) 1.22, 90% interval 1.16 to 1.27. Synonymous variants: 587 observed, 457.85 expected, observed/expected ratio (o/e) 1.28, 90% interval 1.2 to 1.37.